EGF (epidermal growth factor)
Diseases named in the same sentence as EGF in open-access papers (continued):
Sharing a sentence is not in itself a finding about the gene and the disease.
tumor (continued). "Because synovial hyperplasia and pannus formation which invades cartilage and bone leading to joint destruction is similar to a tumor with its neovascularization and cellular infiltration, involvement of EGF and EGFR in RA pathology has been proposed." (PMID 36326383, 2022). "M2 macrophages secrete EGF to activate tumor cell EGFR and upregulate the VEGF/VEGFR signaling pathway to promote tumor cell proliferation and migration." (PMID 36532066, 2022). "Overall, EGF modification mediated selective accumulation of DOX-NPs in the tumor tissues, and RT further enhanced the drug content to therapeutically significant levels." (PMID 35156493, 2022). "Various molecules, such as epidermal growth factor and interleukin-6, can be secreted by CAFs to enhance cell proliferation, tumor invasion and metastasis, and epithelial-mesenchymal transition." (PMID 36465903, 2022). "The formation of a dense ECM is closely related to the secretion of various factors (collagens I, III, IV, and V, as well as VEGFA, EGF, FGF, HGF, and CXCL12) by tumor-associated fibroblasts in tumor tissue." (PMID 35566065, 2022). "To gain further insight into how HIF1α induces CRC progression, we examined the effect of HIF1α on many microenvironmental genes, including TGF-β, TNF-α, VEGF, EGF, PDGF, b-FGF, HGF, and IGF, which have been implicated in promoting tumor development." (PMID 35355718, 2022). "The authors supposed that cytokine release from tumor cells, including tumor necrosis factor-alpha and epidermal growth factor, can induce the maturation of epidermal keratinocytes." (PMID 36291985, 2022). "An attractive finding obtained from the ROC analysis was that DLL4 and EGF levels can be used to differentiate the late stages of disease from early stages, LN involvement from free LN, and high tumor size from low tumor size." (PMID 35681234, 2022). "At the molecular signaling level, we found that Kindlin-2 plays a significant role in regulating BC progression and metastasis in both the cancer cells and the tumor microenvironment (mammary epithelial cells) downstream of a TGF-β/EGF signaling axis." (PMID 35158908, 2022). "We performed EGF/PDGF Signaling Pathway RT2 Profiler PCR arrays to conduct these experiments using SUM-149 tumor samples." (PMID 35681787, 2022). "They considered the density of macrophages, tumor cells, CSF-1, and (EGF) as the main four variables." (PMID 36439180, 2022). "The activation of RSK2 is critical in the cell transformation induced by tumor promoters such as EGF and TPA." (PMID 35964097, 2022). "Hoesl’s analysis of transgenic mice overexpressing LRIG2 showed protein changes in the EGF/ERBB system as well as increased tumor progression with a more rapid development of cSCC-like phenotype." (PMID 35956111, 2022). "MNPs were decorated by the epidermal growth factor (EGF) peptide to be specifically internalized into tumor cells via receptor-mediated endocytosis and then transferred to lysosomes." (PMID 36232435, 2022). "EV-MSCs contain and carry proteins associated with tumor growth and ECM remodeling (TIMP-1, TIMP2, MMP-9, MMP-2), angiogenesis (VEGF and PDGF), proliferation (EGF, TGF-β, FGFs), cytokines including IL-6, IL-8 and IL-1β, RNA and microRNA." (PMID 35741334, 2022). "EPPK1 is part of the epidermal growth factor (EGF) signal and is found to promote the proliferation of tumor cells." (PMID 35505821, 2022). "TAMs directly stimulate cancer cell proliferation through the secretion of epidermal growth factor (EGF), promote tumour angiogenesis by vascular EGF (VEGF) secretion, and remodel the ECM by secreting metalloproteinases (MMPs)." (PMID 35742825, 2022). "Tumor growth is closely related to the epidermal growth factor (EGF) in urine, and the EGF receptor (EGFR) is highly expressed in tumor cells." (PMID 35872872, 2022). "Tumor cells and macrophages can communicate with each other with a set of chemical signalling pathways, mainly EGF and CSF-1." (PMID 36439180, 2022).
tumor (continued). "Crosstalk between OVCA cells and CAFshighα5, moreover, leads to secretion of EGF, which initiates a bidirectional paracrine loop and subsequent increase in tumor cell ITGA5, further stabilizing tumor–stroma interactions." (PMID 35267539, 2022). "GNPs can be modified by ligands or tumor-specific recognition molecules to deliver targeted drugs such as transferrin, folic acid, epidermal growth factor (EGF), or any number of monoclonal antibodies can be conjugated to the surface of GNPs." (PMID 36688039, 2022). "In tumor cells, EGF stimulation resulted in overexpression of JUN/AP1 while inhibition of AKT downregulated it." (PMID 35269445, 2022). "EGF facilitated the adhesion of EGFR+ tumor cells with TAMs through ICAM-1–αMβ2 integrin interaction." (PMID 35682890, 2022). "To determine if the strong statistical association of EGFR-AMPK activity in patient tumor tissue reflects a functional relationship, we stimulated GBM cells with EGF or overexpressed EGFRvIII." (PMID 36130485, 2022). "The EMT process is a critical driver of TNBC metastasis, and EGF is one of the most abundant growth factors in the tumour microenvironment inducing the EMT during local invasion." (PMID 35884900, 2022). "The combination of RT with free DOX or EGF@DOX-NPs exhibited the strongest inhibitory effect on tumor growth, and the growth rate was lowest in the RT + EGF@DOX-NPs group (p < .01)." (PMID 35156493, 2022). "Accordingly, as both molecular signaling pathways are synergistically involved in tumor growth, combining epidermal growth factor (EGF) inhibition with a VEGF inhibitor such as ramucirumab is a rational treatment strategy in EGFR-mutant NSCLC." (PMID 35841410, 2022). "The PI3K/AKT signaling pathway was activated when A2780 and SKOV3 cells were stimulated with EGF, which has been shown to increase tumor proliferation and invasion." (PMID 35645793, 2022). "As a major activator of TAM phenotypes in tumor microenvironment, IL-4 supplied by either T cells or tumor cells can act on TAMs to up-regulate cathepsin enzyme activity in TAMs and augment the EGF/CSF-1 paracrine loop between TAMs and tumor cells." (PMID 35996149, 2022). "Macrophages are known to promote tumor cell migration through the secretion of proteins, such as EGF, CHI3L1, IGF1, FN1, TNC and TGFBI." (PMID 36551640, 2022). "Other tumour-specific ligands, such as epidermal growth factor (EGF), can bind to the receptor EGFR and induce the process of micropinocytosis, which enables nonspecific uptake of cancer-related cargoes." (PMID 36167539, 2022). "N2 TANs can promote angiogenesis and tumor cell proliferation, and secrete tumor necrosis factor TNFα, epidermal growth factor to play a tumor-promoting role." (PMID 35965533, 2022). "Neuregulin has four different types, belonging to the epidermal growth factor (EGF) family of extracellular ligands, which play an essential role in the regulation of cellular growth and tumour formation." (PMID 35886989, 2022). "We investigated phage access in these 3-dimensional tissue models of the CRC stroma and parenchyma with λ phage, both unmodified and with epidermal growth factor (EGF) displayed as a targeting ligand for the EGF receptor on CRC tumor cells." (PMID 36591314, 2022). "Together, our data showed that Kindlin-2, in both the tumor cells and the tumor microenvironment (MECs), is required for the regulation of the TGF-β/EGF signaling axis and subsequent activation of tumor growth." (PMID 35158908, 2022). "Growth factors expressed by TAMs such as epidermal growth factor (EGF) aid tumor cell proliferation." (PMID 36246629, 2022). "Tumors cells secrete CSF-1 to activate macrophages in secreting EGF and subsequently promote tumor growth." (PMID 36439180, 2022). "Mechanistically, EGF secreted by TAMs induced EGFR+ tumor cell migration and TAM spheroid formation through VEGF-C/VEGFR3 signaling." (PMID 35682890, 2022).
tumor (continued). "They provided scenarios of tumor reduction or elimination by decreasing the secretion of CSF-1, EGF, the density of macrophages, chemotaxis sensitivity, and increasing the degradation of CSF-1 or EGF." (PMID 36439180, 2022). "EGF can also increase cancer spread by inhibiting epithelial-mesenchymal transition (EMT) or influencing tumor lymphangiogenesis." (PMID 35655917, 2022). "TGF-α is known as a marker for malignancy due to its tumor transformation ability of normal cells using the EGF pathway." (PMID 36012769, 2022). "RCCM (DMEM/F12+EGF+HC) is therefore a simple medium that reliably sustains survival and growth of tumor cells obtained from dissociated ccRCC samples." (PMID 35965544, 2022). "MSCs in the TME are able to differentiate into TAFs under the influence of various trophic factors, such as TGF-β and epidermal growth factor (EGF), secreted by tumor cells in large quantities." (PMID 35741334, 2022). "Considering that epidermal growth factor (EGF) is overexpressed in many tumor cells, a fusion protein of EGF (ligand) and SPACE (CPP) was constructed to deliver antineoplastic siRNA." (PMID 35890174, 2022). "Epidermal growth factor receptor (EGFR), the receptor for EGF cell proliferation and signal transduction, is related to the inhibition of tumor cell proliferation, angiogenesis, tumor invasion, metastasis, and apoptosis." (PMID 35903247, 2022). "We first used the in vitro assay of JB6 P+ transformation induced by the tumor promoter EGF to examine the effects of gastrointestinal extracts of GLSF and its component GLS." (PMID 35312729, 2022). "It will be interesting to analyse the impact of HA on various anti-tumour mechanisms of SP-D like EGF-EGFR interaction, ICD, and immunomodulation of rfhSP-D besides the previously reported inhibition of SP-D mediated apoptosis of cancer cells." (PMID 35874783, 2022). "Our previously published study showed that Kindlin-2 in tumor cells was involved in the regulation of the CSF1/EGF oncogenic loop, downstream of TGF-β, to activate growth and metastasis of TNBC tumors in mice." (PMID 35158908, 2022). "uPA supports tumor cell proliferation by proteolytically activating various growth factors that include epidermal growth factor (EGF), fibroblast growth factor-2 (FGF-2) and hepatocyte growth factor/scatter factor (HGF-SF)." (PMID 35222418, 2022). "It has been demonstrated that LIMT functions as a tumor-suppressor lncRNA that can be regulated by EGF." (PMID 35526240, 2022). "A phase II trial is currently ongoing to investigate anti-PD-1 in combination with CIMAvax-EGF in a larger cohort of patients, including assessment of biomarkers in pre- and post-treatment tumor tissues." (PMID 35992783, 2022). "TAMs are stimulated by CSF-1 to produce epidermal growth factor (EGF) to strengthen tumor invasion and metastasis." (PMID 35672862, 2022). "Other molecules used for active targeting of polymeric nanoparticles to tumours are transferrin, folic acid, hyaluronic acid and epidermal growth factor (EGF) due to the overexpression of their receptors in cancer cells." (PMID 36005826, 2022). "Studies have shown that gefitinib can effectively inhibit the conduction of the EGF signaling pathway, and overexpression of Cav1 in tumor cells can reduce the inhibitory effect of gefitinib." (PMID 36699336, 2022). "The EGFR has been reported to be expressed in a small proportion of UM cell lines and tumours, and the ligand EGF has been reported to activate the phosphorylation of EGFR and its downstream mediator AKT in EGFR-expressing cell lines." (PMID 35781872, 2022). "CAFs secrete epidermal growth factor (EGF) that upregulates integrin α5 (ITGA5) expression on tumor cells, as well as TGF-β1, leading to strengthened tumor–stromal interactions inside malignant units." (PMID 35682890, 2022). "A significant reduction in tumor volume compared to untreated controls was observed under the influence of Gel-EGF-PCI." (PMID 35744957, 2022).
tumor (continued). "For example, tumor infiltrating myeloid cells release growth factors, such as epidermal growth factor (EGF), hepatocyte growth factor (HGF), and fibroblast growth factor (FGF)." (PMID 36426359, 2022). "Remarkably, most of the 20 prioritized ligands such as APP, EGF, and IL6, were associated with the process of tumor formation, progression, and invasion as well as confronting the anti-tumor immune response." (PMID 35812726, 2022). "Epidermal growth factor (EGF) is the ligand of EGF receptor (EGFR) overexpressed on the surface of various tumor cells." (PMID 34915901, 2021). "Consistently, Literatures have demonstrated that the SMAD3 and Erk pathways are also regulated by other factors in the tumor environment including steroid hormones and epidermal growth factor." (PMID 33602253, 2021). "Similar to EGFRAP, SOCS proteins, such as Drosophila Socs36E and its human ortholog SOCS5, also contain an SH2 domain, are induced by EGF stimulation and behave as tumor suppressors in cooperation with the EGFR/Ras pathway." (PMID 34411095, 2021). "Tumor-associated macrophages (TAMs) are an important source of many factors inducing EMP, including tumor growth factor beta (TGF-β), Wnt-1, EGF and IL-8." (PMID 34072345, 2021). "Previously, our group reported AP-1 as a major transcription factor in the transformation of JB6 Cl41 cells that is induced by various tumor promoters, such as epidermal growth factor and 12-O-tetradecanoylphorbol 13-acetate." (PMID 33800170, 2021). "Platelets are important sources of EGF and known to be present in and around extravascular tumor tissue and can thus be presumed to play an active role in this context." (PMID 33791226, 2021). "In other cases, EGF cooperates with other cytokines, e.g., TNFα, to promote the motility of tumor cells." (PMID 34572344, 2021). "As a consequence of this blockade, extracellular activators like the epidermal growth factor (EGF) cannot bind to the receptor anymore and tumour-promoting downstream signalling cascades cannot be activated." (PMID 33150521, 2021). "CTX specifically binds with EGFR expressed on the tumor cell membrane and competitively blocks EGF and other ligands, subsequently inhibiting downstream signals." (PMID 34385595, 2021). "Epidermal growth factor (EGF) is the expression product of the oncogene cerbB1 and has been shown to be associated with poor tumor prognosis in numerous studies." (PMID 34823489, 2021). "The N2 phenotype promotes tumor invasion and metastasis; enforcement of angiogenesis; and expression of epidermal growth factor (EGF), transforming growth factor β (TGF-β), platelet-derived growth factor (PDGF) and vascular endothelial growth factor (VEGF)." (PMID 34835236, 2021). "Availability and spatial distribution of EGF within tumors will most probably further contribute to intra-tumor heterogeneity, as has been described for TGFβ during the induction of pEMT." (PMID 34771518, 2021). "We used tumor-like EGF and stiffness conditions to interlink CP regulation with invasive cell transition." (PMID 34440749, 2021). "Distinct from their normal counterparts, tumor endothelial cells are more responsive to EGF incubation with activation of mitogen-activated protein kinase (MAPK) signaling pathways and increased proliferation." (PMID 34680445, 2021). "Previous reports have shown that IFNγ increases the expression of MHC class I molecules in tumor cells, while EGF decreases it." (PMID 33491334, 2021). "EGF can activate several pro-oncogenic intracellular pathways leading to tumour cell proliferation and angiogenesis." (PMID 34358255, 2021). "As EGF signaling can induce PD-L1 upregulation in tumor cells, thereby shielding the tumor from the immune system, co-expression of both proteins occurs predominantly on cancer cells." (PMID 34040611, 2021).
tumor (continued). "Aberrant epidermal growth factor (EGF) and IGF signalling are detected in TNBC tumours and are linked to higher rates of recurrence, poor response to therapy, and reduced overall survival." (PMID 35011656, 2021). "CIMAvax-EGF administration induces antibodies against EGF, prevents EGF from binding to its receptor, and, therefore, inhibits tumor growth." (PMID 34201650, 2021). "Thanks to its high binding affinity to the EGFR receptor, several EGFR-binding ligands, such as EGF or its functional fragments, were proposed as decorating molecules for anti-tumour drug-loaded nanoparticle surfaces to achieve tumour cell-specific delivery." (PMID 33808586, 2021). "Da Huang Wan, a traditional herbal medicine, also decreased tumor progression in vitro by modulating EGF." (PMID 34572344, 2021). "In contrast, the same movement of EGF-triggered SF cells at the BM–ECM interface with tumor-like stiffness leads to imbalanced solid stresses." (PMID 34440749, 2021). "EGF is an important growth factor promoting tumor growth and ERK is a pivotal downstream effector of EGF." (PMID 35201498, 2021). "The ability of exosome surface-expressing ligands or receptors like those for growth factors like epidermal growth factor (EGF) to target EGF-R-expressing tumor cells, as well as enzymes, and inhibitors like TGFβ–1 enables them to target cancer cells." (PMID 33572657, 2021). "Epidermal Growth Factor (EGF) secreted by TAMs can make tumor cells form elongated protrusions and enhance their invasion ability." (PMID 33391402, 2021). "This study intended to improve the anti-tumor efficacy of EGF-GNPs by anticipating the reduced activity of the conjugated EGF molecule on the nanoparticle surface in early work." (PMID 34512175, 2021). "Inhibition of lymphokine-activated killer T-cell-originated protein kinase (TOPK) (64% at 400 μg/mL) and EGF-downstream signaling. ↓ Tumor growth 72% at 50 mg/kg." (PMID 34436263, 2021). "In particular, TAMs produce a large array of soluble mediators to support tumor cell proliferation, such as Epidermal Growth Factor (EGF), Platelet-derived Growth Factors (PDGF) and Vascular Endothelial Growth Factor (VEGF)." (PMID 34583655, 2021). "In accordance with the hyperactivation of the oncogenic EGF/Ras signaling pathway and the rapid tumor progression, Vegfa and Hif1α expression was significantly upregulated in PyMT;Sirt7+/− tumors." (PMID 34433808, 2021). "In the A431 tumor mouse model, EGF-PMBN-PTX suppressed tumor growth significantly compared to PMBN-PTX and saline." (PMID 33530291, 2021). "Currently, several chemical inhibitors against EGFR were developed, considering the important biological impact of EGF and their receptors in tumor cells." (PMID 34445562, 2021). "PHD3 knockdown reduced HIF2α expression and increased phosphorylated epidermal growth factor (EGFR) expression in untreated tumor models." (PMID 33799686, 2021). "For example, platelet-derived growth factor (PDGF), epidermal growth factor (EGF), tumor necrosis factor α (TNFα), interleukin-1 (IL-1), transforming growth factor β (TGFβ), etc. can stimulate ROS production and promote tumor progression." (PMID 33673398, 2021). "In the tumor microenvironment, CAFs interact with other cells through direct cell-to-cell contact and by secreting cytokines such as TGFβ1, epidermal growth factor (EGF), hepatocyte growth factor (HGF), and interleukin 6 (IL-6)." (PMID 34095135, 2021). "Then, TAMs release epidermal growth factor and angiogenic factors to promote tumour cell proliferation and migration 27-29." (PMID 33995642, 2021). "Intravital imaging revealed that macrophages utilize M-CSF to communicate with tumor cells via a paracrine loop of M-CSF secreted by tumor cells and EGF secreted by macrophages." (PMID 34832904, 2021). "During the first 24 h, the cells remained inside the tumor region, whereas after 24 h, EGF stimulated cells started invading the stromal region." (PMID 33417986, 2021).